IL1A (interleukin 1 alpha)
Diseases named in the same sentence as IL1A in open-access papers (continued):
Sharing a sentence is not in itself a finding about the gene and the disease.
diabetes (40 papers, 2010 to 2025). "Diabetes affects the expression of pro-healing DC indicators such as IL-1a, suggesting that these crucial innate immune cells may contribute to diabetes-associated immunological dysregulation." (PMID 39538179, 2024). "We found that treatment with either MSI-1436 or AAV2-Cryba1 construct for 2 months following diabetes onset did reduce IL-6 and IL-1α levels as well as capillary degeneration." (PMID 33627831, 2021). "Our findings are strongly supported by previous reports that IL-1α-889 C/T polymorphism and IL-1 receptor antagonist allele (IL1RN*2) were associated with nephropathy in diabetes mellitus." (PMID 32733443, 2020). "These patterns of oral hygiene based on the plaque and gingival bleeding indexes were evaluated based on age, sex, ethnic background, interleukin 1 alpha and beta genotypes, diabetes status, smoking habits, and other concomitant diseases." (PMID 29716557, 2018). "Using the precise sequence information of INS/IL-1α motif, development of a neutralizing antibody against the ligands and receptors will shed light on the specific role of pINSd and IL-1α in diabetes." (PMID 27226621, 2016). "Moreover, YME1L overexpression led to reduced mRNA abundance of common SASP markers, including Tgf-β, Il-6, IL-1α, and Tnf-α, compared with control mice with diabetes." (PMID 38494498, 2024). "Although the differences between diabetes at the site of skin damage were statistically significant for IL‐1α at the second sample collection timepoint, the corresponding range for patients with and without diabetes were similar, ranging between 5007–21 855 and 438–21 478 pg/mL, respectively." (PMID 36872612, 2023). "In addition, diabetes-induced increases in retinal inflammatory proteins iNOS, IL-1α, and IL-10, and ICAM-1 were also inhibited in STING-KO and STINGGT diabetic mice." (PMID 37345657, 2023). "Furthermore, increased basal IL‐1α and IL‐1β expression levels can lead to the development of the type 2 diabetes mellitus phenotype." (PMID 26660555, 2015). "To understand the mechanism underlying the effects of ASCs on CAIA, we examined the serum levels of five cytokines (IL-15, IL-1α, IL-6, IL-7, and TNFα), five diabetes-related hormones (resistin, GIP, GLP-1, ghrelin, and leptin), and adiponectin using multiplex immunoassays." (PMID 26210906, 2015). "Several predicted interactions were observed, many of them encompassing genes involved in the pathogenesis of diabetes, for instance miR-30e targeting IL1A and IRS2, miR-181a targeting IL1A, miR-223 targeting SLC11A2, miR-29b targeting ID1, miR-21 targeting CCL20, and many others." (PMID 24279768, 2013). "Indeed, the results presented here demonstrate that blocking type I IFN signaling during diabetes partially yet significantly restored the levels of IL-1α, IL-1β, and IL-6." (PMID 23533683, 2013). "Thus, blocking type I IFN signaling during diabetes partially but significantly restored the levels of IL-1α, IL-1β, IL-6, and CXCL10." (PMID 23533683, 2013). "Therefore, the present study investigated whether miR-30a regulates immune and islet cell inflammation and function by targeting IL-1α and found that 30a serves as a promising buffer and response factor in inflammatory diseases including diabetes." (PMID 28706254, 2017). "Among subjects with diabetes, those with TIR ≤ 70% had higher levels of IL-1α, IL-1β, IL-6, IL-12 p70, IL-16, LIF, M-CSF, MCP-1, MCP-3, RANTES, TNF-α, TNF-β, and b-NGF, and lower levels of IL-1α, IL-4, IL-10, GM-CSF, and MIF than individuals with TIR > 70%." (PMID 37893217, 2023). "The increasing IL-6, IL-1α, TNF-α and TGF-β expression in the lungs of diabetic rats indicates that the expression of proinflammatory cytokines was upregulated in diabetes and was downregulated by insulin and Rb1 treatment." (PMID 36367996, 2022). "SASP genes (i.e., IL-1α, IL-1β, IL-6, and TNF-α) are chronically activated in cells and tissues from diabetes patients." (PMID 27340505, 2016).
diabetes (continued). "IL-1α and IL-1β protein levels were significantly reduced in lumbar DRG and in sciatic nerve at 2 and 5 months of diabetes (*p<0.05 vs diabetic)." (PMID 24152426, 2013). "In the diabetic mice, we observed aberrant and significantly elevated levels of IL-1α, IL-1β, IL-6 and CXCL10 compared to the control group, which indicated prolonged proinflammatory conditions during diabetes." (PMID 23533683, 2013). "These included inflammatory cytokines (IL-1α, IL-6 andTNF-α), oxidized LDL (oxLDL) that model the inflammatory environment of atherosclerotic plaques, and metabolic stressors (high glucose and low serum) that reflect diabetic vascular dysfunction." (PMID 41332607, 2025). "We first found that diabetes induction was accompanied by an elevation in the plasma levels of reactive oxygen species (ROS), hydroperoxide, malondialdehyde (MDN), and the proinflammatory cytokines IL-1α, IL-1β, IL-6, and CXCL10." (PMID 23533683, 2013). "Elisa analysis demonstrated that diabetes increased the levels of left ventricular IL-6, IL-1α and tumor necrosis factor-α (TNF-α) as compared with the non-diabetic group." (PMID 22432030, 2012). "Diabetes increased TLR4-mediated inflammation, whereas DP inhibited the protein expression of the TLR4 pathway (TLR4, Myd88, IRAK1, and TRAF6) and reduced the mRNA expressions of IL-1β, IL-1α, IL-6, and TNF-α and the protein expressions of TNF-α, IL-1β, and COX-2." (PMID 35463063, 2022). "However, the associations between IL1A and IL1B polymorphisms and IA were not significant after adjusting for age, smoking, drinking, diabetes, and hyperlipidemia status." (PMID 33511216, 2021). "Therefore, the significantly reduced cytokines (IL-1α, IL-6 and TNFα) levels in the hippocampus of the DB and DAV groups, contrary to previous reported increases, may suggest a compromised immune response and prolonged diabetes." (PMID 35453953, 2022). "However, to our knowledge, no study has investigated IL-1α in adults with long-term diabetes." (PMID 32908447, 2020). "However, IL-1α and IL-1ra are not significantly elevated and may not contribute to the pathophysiology that increases the frequency of diabetes in overweight adolescents." (PMID 20169140, 2010).
Arthritis (38 papers, 2005 to 2025). Inflammation of a joint. "It was also found that in mice transgenic for IL-1α (activation of IL-1 signalling) and prone to arthritis, IL-6 deficiency resulting from knockout of the corresponding gene reduces, but does not cancel, pathological changes in the joints." (PMID 36911042, 2023). "The inflammatory parameters of the TTP deficiency syndrome (weight gain deficits and arthritis) were in general only slightly less pronounced in Il1a−/−TTP−/− and Il1b−/−TTP−/− mice as compared to TTP−/− animals." (PMID 32733464, 2020). "Mice deficient in IL-1α, IL-1β, and IL-1α/β suppress arthritis in a mouse model, suggesting that both forms of IL-1 are required for inflammatory bone loss." (PMID 28289415, 2017). "Overexpression of IL-1α or IL-1β or deficiency of the soluble IL-1Ra in arthritis models resulted in the development of disease, which is associated with bone and cartilage destruction." (PMID 26634933, 2016). "IL-1α and IL-1β are also expressed in abundance in the synovial membrane, and IL-1Rα-deficient mice develop spontaneous arthritis, mediated in part by amplification of Th17-dependent inflammation." (PMID 26284069, 2015). "Membrane associated IL-1α contributes to arthritis in a mouse model, so modulating IL-1α KFA could have therapeutic applications." (PMID 34368168, 2021). "Additionally, patients with single nucleotide polymorphisms (SNPs) in Myd88, Il1a, and Il1r1 genes have an increased risk of osteomyelitis and inflammatory joint disorders, further underscoring the importance of these immune pathways in skeletal homeostasis." (PMID 30978245, 2019). "Gene expression intensities were much higher in the arthritis-affected rams than in the healthy ones for the genes IL-1α, IL-1β, IL-6, IL-10, TNFα, NCF4, NFKB, TMED, FCAMR, iNOS and COX18." (PMID 40005882, 2025). "The rams with arthritis showed significantly greater levels of gene expression for the genes IL-1α, IL-1β, IL-6, IL-10, TNFα, NCF4, NFKB, TMED, FCAMR, iNOS and COX18 than did the healthy rams." (PMID 40005882, 2025). "When comparing healthy rams to those with arthritis, the expression levels of the following genes were noticeably higher: IL-1α, IL-1β, IL-6, IL-10, TNFα, NCF4, NFKB, TMED, FCAMR, iNOS and COX18." (PMID 40005882, 2025). "Studies have found that Nos2-induced NO promotes mannose-induced Ps and PsA models (MIP) in mice, and Nos2-dependent IL-1α is essential for arthritis development by promoting IL-17 production of innate lymphoid cells." (PMID 38035065, 2023). "Targeting IL1R signaling by administrating anti-IL1α/β or IL1RA ameliorates arthritis in the collagen-induced arthritis (CIA) mouse model." (PMID 35567665, 2022). "Among the polymorphisms found more frequently in AS patients with arthritis, JAK2 rs7857730, IL-23R rs11209008 and rs10489630, CYP1B1 rs1056836, NELL1 rs8176786, KL rs564481, MEFV rs224204, IL-2RB rs743777, and IL-1A rs1800587 have been described." (PMID 35629038, 2022). "We also observed a concomitant increase in the levels of many cytokines, including IL-1β, IL-6, TNF-α, and IL-1α, in knee homogenates in WT mice after arthritis induction." (PMID 35439173, 2022). "Expression of NLRP3, caspase-1, and IL-1 is increased in the synovial tissues of CIA mice, and IL-1α, IL-1β, and IL-1αβ-deficient mice are less sensitive to CIA-induced arthritis." (PMID 35628185, 2022). "M2 macrophages produce anti-inflammatory cytokines, such as IL-10, IL-1α, transforming growth factor β, and tissue repair factors, leading to resolution of inflammation and suppression of arthritis." (PMID 34831223, 2021). "EGCG decreased the arthritis index and showed protective effects against joint destruction in an IL-1α knock out arthritis model." (PMID 30936628, 2019). "For example, van den Berg and coworkers showed that a combination of antibodies to IL-1α and IL-1β given before the onset of arthritis completely prevented murine CIA." (PMID 16207337, 2005).
Arthritis (continued). "IL-1α induces the production of granulocyte-macrophage colony-stimulating factor (GM-CSF) and granulocyte colony-stimulating factor (G-CSF) by fibroblasts in arthritis, arthrofibrosis, and skin fibrosis." (PMID 40705472, 2025). "In our experiment, LBP relieved the typical features of RA in rats, including the reduction of paw swell, arthritis scores and the contents of pro-inflammatory cytokines such as IL-1α, IL-1β, IL-12 and IL-17, and the recovery of the content of anti-inflammatory cytokine IL-10." (PMID 35864275, 2022). "Platelet IL-1α also drives arthritis and cerebrovascular inflammation after ischaemia, and thus platelet-derived p18 IL-1α may be involved in these settings too." (PMID 30926232, 2019). "Interleukin-1α (IL-1α) is a 19 kDa proinflammatory cytokine that is a potent mediator of the body's response to inflammation, microbial invasion, tissue injury, and immunological response, and has a role in arthritis, Alzheimer's disease and tumor growth." (PMID 21162738, 2010). "Importantly, K/B × N arthritis clinical severity and inflammatory profile was dependent on IL-1R expression, the essential IL-1R signalling adaptor Myd88, and both the IL-1R ligands, IL-1α and IL-1β." (PMID 25693118, 2015). "The 70 % mark of arthritis incidence was reached at 9 weeks of age in Il1b−/−TTP−/− mice and at 15 weeks of age in Il1a−/−TTP−/− mice." (PMID 32733464, 2020). "TGs, which derived from botanical materials, exhibits immune-suppressive functions, and also attenuates inflammation and arthritis through reducing PGE2 production and levels of IL-1α, IL-1β, TNF-α and IL-6." (PMID 32503513, 2020). "In our study of K/BxN serum-induced arthritis, IL-12 p40 levels had not been different, and IL-6 and M-CSF levels tended to be altered in tg mice in comparison to WT mice (IL-1α and IL-13 levels were not determined)." (PMID 24491163, 2014). "Our results demonstrate up to 125 fold increases in synovial IL1α and IL1β concentrations, approximately 30 fold increases in levels of IL6 and IL10 and a 200–300 fold elevation in synovial concentrations of TNFα during FCA-induced experimental arthritis." (PMID 17567894, 2007). "Zymosan caused systemic inflammation with a marked elevation in multiple pro- and anti-inflammatory cytokines TNF-α, IFN-γ, IL-13, G-CSF, M-CSF, IL-6, IL-18, IL-1α and IL-4 in arthritic rats (all arthritis groups pooled) versus the non-arthritic controls (0.001<p<0.05)." (PMID 33878143, 2021). "The upregulated expression of TNF-α, IL-1α, IL-1β, IL-4R, P-selectin, MIP-1α (CCL3), MCP-1 (CCL2), NOS2 and NOS3 demonstrated in the present study is in agreement with previous observations of the dependency of the rat SCW-induced arthritis model on these mediators." (PMID 15642130, 2005). "This research described the antioxidant (SOD3, CAT, GPX, ATOX1 and COX18) and immunological (IL-1α, IL-1β, IL-6, IL-10, TNFα, NCF4, NFKB, TMED, FCAMR and iNOS) genes in rams that had arthritis and those that did not." (PMID 40005882, 2025). "The levels of IL-1α and IL-17A did not change in the setting of CFA-induced arthritis." (PMID 36293292, 2022). "However, the comparison of Il1a−/−TTP−/− and Il1b−/−TTP−/− mice suggests that IL-1α might contribute more to the lack of fertility and to arthritis, whereas IL-1β plays a more critical role in the weight gain deficit." (PMID 32733464, 2020).
asthma (38 papers, 2012 to 2024). "For example, nasal polyposis is driven by asthma‐associated chronic inflammation, while systemic sclerosis is an autoimmune disease with a strong inflammatory component, and thus less IL‐1α would understandably benefit." (PMID 36175368, 2023). "Moreover, DAPP1 expression in the lung was highly positively correlated with a panel of pro-inflammatory cytokines, including several that have been implicated in asthma, such as IL1A, IL7, IL12A, IL17A, IL23A, and IL33." (PMID 31869344, 2019). "IL-1α is increased in the BAL of asthma patients with neutrophilia compared to a more type 2-associated asthma." (PMID 37445635, 2023). "For the inflammatory cytokines in the lung, the contents of TNF-α, TNFR2, CXCL-9, CCL-12, CCL-9, CCL-2, and CCL-5 in the asthma model group were higher than those in the control group, while the contents of GM-CSF and IL-1α were decreased." (PMID 35600943, 2022). "Different IL1A expressions in airway epithelium of asthma patients were identified according to various microbiome profiles." (PMID 36076228, 2022). "Single nucleotide polymorphisms (SNPs) in IL1A, IL1B, and IL1R1 are all linked to asthma; accordingly, IL-1α and IL-1β both exacerbate murine allergic airway inflammation." (PMID 35281022, 2022). "Patients with severe fungal-sensitized asthma have higher levels of IL-1α/β and IL-1Ra, indicating the antagonist is involved." (PMID 33643264, 2021). "Further, IL-1α/β can affect airway fibroblast-driven inflammation and collagen I formation, which has implications for airway remodeling in asthma." (PMID 32457454, 2020). "Microbial adhesion (virulence) and Proteobacteria abundance were significantly associated with variation in the expression of the upstream regulator IL1A; suggesting that microbiome characteristics modulate host inflammatory and immune systems during asthma." (PMID 26125632, 2015). "The involvement of IL-1β in an OVA-induced asthma model was demonstrated in attenuated airway hypersensitivity response (AHR) in IL-1α/β knockout mice and reduced airway eosinophilic inflammation and goblet cell hyperplasia in mice lacking the IL-1β receptor." (PMID 24671176, 2014). "Additionally, wedelolactone inhibited the IL-1α, IL-1β, IL-6 and IL-17a mRNA expression, which were related to neutrophilic predominant asthma." (PMID 38459541, 2024). "Despite these advancements, there remain significant gaps in our understanding, particularly regarding the role of less conventional alarmins like HMGB1, IL-1α, IL-36 and TL1A in asthma pathology, as well as genetic factors that predispose patients to respond to specific biologics." (PMID 39457624, 2024). "In addition, the contents of TNF-α, TNFR2, CXCL-9, CCL-12, CCL-9, CCL-2, and CCL-5 in the asthma model group were higher than those in the control group, while the contents of GM-CSF and IL-1α were decreased." (PMID 35600943, 2022). "In a mice model of severe asthma, Bifidobacterium breve significantly decreased the levels of the pro-inflammatory cytokines IL-1α and IL-1b and the chemokine CXCL-2, which stimulate neutrophil migration to pulmonary tissue, as compared with control, where an increase of IL-1α was observed." (PMID 33194897, 2020). "Indeed, in a murine asthma model, it was shown that IL1α release by pulmonary epithelial cells induces allergic sensitization to inhaled house dust mite via autocrine release of Th2-driving cytokines IL25, IL33, and TSLP." (PMID 31427886, 2019). "The predictive equation for FEV1% predicted in asthma was 103–0.023 (IL-8) + 0.040 (IL-1α)." (PMID 26011707, 2015). "Compared to healthy control subjects, patients with asthma had significantly more percentages of eosinophils and neutrophils, IL-1RA, IL-1α, IL-1β, IL-2Rα, IL-5, IL-6, IL-7, IL-8, G-CSF, GROα (CXCL1), MIP-1β (CCL4), MIG (CXCL9), RANTES (CCL5) and TRAIL in their BAL fluids." (PMID 26011707, 2015). "IL-1α is a potent activator of fibroblasts and might play a role in fibroblast activation and hyperplasia in asthma." (PMID 23398985, 2013).